RNU6-425P (RNA, U6 small nuclear 425, pseudogene)
Gene: Small nuclear RNA gene on chromosome 3 (142,145,454 to 142,145,555, forward strand). Ensembl gene ENSG00000206604.
Homologues: Orthologues: chimpanzee U6 (99% identical), macaque U6 (95% identical), guinea pig U6 (86% identical), dog U6 (85% identical), guinea pig U6 (81% identical). Paralogues in human: RNU6-558P (86% identical), RNU6-1011P (85% identical), RNU6-1060P (85% identical), RNU6-116P (85% identical), RNU6-12P (85% identical), RNU6-13P (85% identical), RNU6-15P (85% identical), RNU6-32P (85% identical), RNU6-33P (85% identical), RNU6-41P (85% identical), RNU6-47P (85% identical), RNU6-73P (85% identical), and 1288 more.